IL17A (interleukin 17A)
Diseases named in the same sentence as IL17A in open-access papers (continued):
Sharing a sentence is not in itself a finding about the gene and the disease.
psoriasis (continued). "The immunologic pathogenesis of psoriasis involves the continuous action of TNF‐α, IL‐23, and IL‐17A from upstream to form the skin rash." (PMID 37305885, 2023). "The data in our study showed that glycyrrhizic acid compound ointment inhibited inflammatory cytokines including TNF-α, IL-12, IL-17A, and IL-23 in the skin of IMQ-induced psoriasis-like mice, and the inhibitory effect became stronger with increasing dose." (PMID 37643205, 2023). "In the MatTek tissue model of psoriasis, the application of GSH alone resulted in strong inhibition of the expression both of the cell replication marker Ki67 and the inflammatory markers IL17A, IL23, TNF alpha, and TNF beta." (PMID 37469991, 2023). "Human IL-37b inhibits the production of CXCL8, IL-6, and S100A7, which are important in the pathogenesis of psoriasis, in keratinocytes stimulated with inflammatory cytokines (TNF-α, IL-17A, IL-22, IL-1α, and Oncostatin-M)." (PMID 37834081, 2023). "Previous studies have demonstrated that this signaling molecule is involved in the pathogenesis of psoriasis by upregulating the production of chemokines and pro-inflammatory cytokines, such as IL-6, TNF-α and IL-17A." (PMID 36839031, 2023). "Among the common induced pathways, we identified IL-17A and ERK/MAPK signaling, both known to be fundamentally involved in atopic dermatitis and psoriasis." (PMID 37539048, 2023). "Through intragastric administration, CUR can alleviate psoriasis‐like lesions of mice by decreasing PASI scores, reducing the level of IL‐6, IL‐17A, IL‐22, IL‐23, TNF‐α, and TGF‐β1, promoting the expression of IL‐10." (PMID 37647442, 2023). "Local immune memory in psoriasis is well understood: CD8+ CD103+CD49a‐TRM express CCR6 and produce IL‐17A, and CD4+ TRM produce IL‐22." (PMID 37144705, 2023). "The regulation of IL-17A and TNF-α engages distinct pathogenetic mechanisms, with IL-17A/IL-23 as the primary pathogenetic axis in psoriasis, while TNF-α assumes a supportive role." (PMID 38239345, 2023). "considered ongoing clinical trials of anti-IL-17a drugs as well as FDA and EMA approved medication (for patients of psoriasis and arthritis) and generally found them to be safe and well tolerated." (PMID 37483613, 2023). "The interleukin (IL)23A/IL17A and the tumor necrosis factor (TNF)α/nuclear factor (NF)-κB signaling pathways are considered critical in the pathomechanism of psoriasis." (PMID 37351597, 2023). "Consistent with this, we now demonstrate that the strongest IL-17A and TNF downstream responses in psoriasis are in the supraspinous compartment." (PMID 37308489, 2023). "Subsequently, we established an IL-17A treated STAT3 overexpressing mouse model, exhibiting typical pathological psoriasis features such as abnormal proliferation and differentiation of epidermal cells." (PMID 37465147, 2023). "Here, we investigated the consequences of an anti-IL36R treatment in two mouse models of IL-17A-driven psoriasis: in IMQ-treated mice and in mice that overexpress IL-17A in the epidermis, thus developing IL-17A-depending psoriatic lesions." (PMID 38162658, 2023). "Lactobacillus probiotics have been successfully used in vitro in imiquimoid-induced psoriasis in mice, resulting in lower gene expression levels of pro-inflammatory markers such as TNF-α, IL-19, IL-17A, and IL-23, as well as lower PASI scores." (PMID 37895330, 2023). "For example, secukinumab, an agent targeting IL-17A, is an FDA-approved therapy for psoriasis, psoriatic arthritis, and ankylosing spondylitis." (PMID 37115755, 2023). "After systemic IL-17A blockade, the expression of KRT15 was increased in posttreatment psoriasis lesional skin KCs compared to pretreatment psoriasis lesional skin KCs (p < 0.05)." (PMID 37781383, 2023). "The aberrant type 1/17 immune responses represent a predominant mechanism in psoriasis due to the abundant release of type 1/17 cytokines such as IFN-γ, IL-17A, IL-23, and tumor necrosis factor (TNF)-α." (PMID 37259392, 2023).
psoriasis (continued). "Statistically significant correlations were also observed between baseline IL-17A, IL-17F, and IL-22 levels and baseline PASI score as well as between IL-17A and IL-17F levels and BSA affected by psoriasis." (PMID 37587493, 2023). "To further investigate the role of epidermal CD147 in regulating the energy metabolism of KCs in psoriasis, we conducted glycolysis stress tests in the KCs of K14.Bsgfl/fl transgenic mice treated with IMQ or IL-17A." (PMID 37303600, 2023). "After IL-17A blockade, KC expression of IL36G, S100A8, DEFB4A, and DEFB4B in S. corneum and S. granulosum decreased in posttreatment psoriasis lesional skin compared to pretreatment psoriasis lesional skin (p < 0.05)." (PMID 37781383, 2023). "The exact cause of psoriasis is not fully understood, though it has been reported that proinflammatory cytokines such as IL-17A, TNF-α, and IFN-γ play an important role in the pathogenesis of psoriasis." (PMID 37686332, 2023). "Particularly, the cytokine IL17A, primarily generated by TH17 cells, assumes a crucial function in the etiology of psoriasis." (PMID 37816883, 2023). "The DEGs between IL-17A treated STAT3 mice and WT mice were highly consistent with those observed in psoriasis patients, including S100A8, S100A9, Sprr2, and LCE." (PMID 37465147, 2023). "After IL-17A blockade, KC expression of KRT15 in S. basale increased in posttreatment psoriasis lesional skin compared to pretreatment psoriasis lesional skin (p < 0.05)." (PMID 37781383, 2023). "We further showed induction of CXCL12 in HMEC-1 cells by either mixture of pro-inflammatory cytokines (IL-17A, IL-22, TNF, IL-1α, and oncostatin M), or serum from active psoriasis patients." (PMID 37736772, 2023). "Circulating blood levels and titer in skin lesions of TH1 cytokines (e.g., IFNγ, IL-2, TNFα) and TH17 cytokines (e.g., IL17A, IL17F, IL22, IL26) are significantly increasedin active psoriasis, as well as eruptive lesion IL23, IL20 and IL15." (PMID 37885781, 2023). "Our results showed that spleen weight and cytokine levels, including IL-17A, IL-22, IL-23, IL-6, and IFN-γ, increased in the IMQ-induced psoriasis-like dermatitis mice." (PMID 35682849, 2022). "In turn, IL-17A promotes keratinocytes to produce CCL20, and Th17 cells can also produce CCL20, which forms positive feedback in the pathogenesis of psoriasis." (PMID 36620087, 2022). "Remarkably, the ratios of autoantibodies to cytokines of IL-22, IL-17A, and IFN-γ were significantly decreased, whereas the ratio of anti-IL-8 antibody to IL-8 was elevated in patients with psoriasis." (PMID 36118416, 2022). "Clearly, there is some disputation regarding the results on serum IL-17A levels and its correlation with disease severity assessed by PASI in psoriasis." (PMID 35340911, 2022). "They identified IL17A and KLK7 as biomarkers for disease severity and apremilast pharmacodynamic effects in psoriasis patients." (PMID 35327421, 2022). "When the profile of CD4+ T cell subsets in the spleen and draining lymph node (dLN) of the psoriasis animal model was examined, the high level of T-bet+ or IFN-γ+ CD4+ T cells and ROR-γt+ or IL-17A+ CD4+ T cells was detected in psoriasis-induced mice." (PMID 36591260, 2022). "To evaluate the potential pharmacological effect of PUN on psoriasis, we made use of imiquimod (IMQ)-induced psoriasis-like mice model and tumor necrosis factor α (TNF-α) and IL-17A-stimulated HaCaT cells." (PMID 35153790, 2022). "The pathogenesis of psoriasis includes excessive proinflammatory cytokines, such as IFN-γ, TNF-α, IL-17, IL-22, and IL-23, among which IL-17A plays a key role." (PMID 35745784, 2022). "In patients with psoriasis, an increase in the CD8 and CD69, IL-17A and IL-22 immunoreactive area in the epidermis was found, but it did not change significantly in the dermis compared to the control group." (PMID 35886201, 2022).
psoriasis (continued). "An earlier report showed that Th17 family of cytokines (IL-17A and IL-17F) secreted by skin contained infiltrating γδ T cells and RORγt+ innate lymphocytes, which promoted the initiation of IMQ-induced psoriasis." (PMID 35663991, 2022). "Overall, our data indicated that CMTM4 regulates IL-17A signaling in vivo and mediates IMQ-induced psoriasis, while it had only a limited role in MOG-induced EAE." (PMID 36271145, 2022). "We next analyzed the correlations across cytokines, because cytokines such as IL-17A and TNF-α were well known to work synergistically in human keratinocytes to promote inflammation in psoriasis." (PMID 36118416, 2022). "In conclusion, we demonstrated that IRh improved IMQ-induced psoriasis-like dermatitis by decreasing TNF-α, IL-6, IL-17A, and nuclear NF-κB levels in the skin, and increasing malondialdehyde (MDA) levels in plasma." (PMID 36556472, 2022). "This study did not identify two well-known cytokines that play an essential role in the pathogenesis of psoriasis and as drug targets (TNF-α and IL-17A)." (PMID 36483564, 2022). "The loss of IL-17A/PASI correlation in the presence of atherosclerotic CVD, together with the decreased correlations of PI3, IL-17C, CCL20 and TGF-α with PASI in these patients, clearly merits further investigation and may contribute to further understanding of the links between psoriasis and CVD." (PMID 35008981, 2022). "Both psoriasis and IBD are associated with T-cell activation and production of proinflammatory cytokines, such as IL-17A, IL-23, and TNF-α, but biologics targeting IL-17A, IL-23, or TNF-α showed different therapeutic effects in psoriasis or IBD patients." (PMID 35801760, 2022). "As a result, in patients with moderate-to-severe psoriasis, we propose circulating IL-17C and PI3 as potential biomarkers of effective systemic anti-psoriatic treatment, and IL-17A as potential marker of CVD." (PMID 35008981, 2022). "Secukinumab (Anti-IL-17A antibody) and Fontolizumab (anti-IFN-γ antibody) are being tested in rheumatoid arthritis (RA) (NCT00281294) and psoriasis (NCT04711902, NCT04632927)." (PMID 36591260, 2022). "Moreover, the concentrations of IFN-γ, TNF-α, IL-17A, and IL-23 in skin lesions and serum of mice decreased significantly, suggesting that hUC-MSCs and indirubin are involved in the process of immune regulation in the treatment of psoriasis, and the targets and focuses are different." (PMID 36466901, 2022). "In the present study, we found that CB2R KO contributed to the pathogenesis of psoriasis by promoting CD4+ T cell proliferation; upregulating Th17 cytokines, such as IL-17A, IL-23A, and IL-17C; and downregulating IL-10." (PMID 35173615, 2022). "Psoriasis is an autoimmune inflammatory disease characterized by cytokines elevated, including TNF-α, IL-1β, IL-6, and IL-17A." (PMID 35860030, 2022). "The levels of inflammatory TH17 cytokines (IL-17A, IL-22 and IL-23) and TH1 cytokines (IL-1β, IFN-γ and TNF-α) were also measured in the skin; psoriasis is considered to be regulated by TH17 and TH1 responses." (PMID 35562873, 2022). "Treatment with compound A ameliorated psoriasis skin lesions and suppressed the number of CD4+IL-17A+ T cells in the lymph nodes and the spleen in an FFA4-dependent manner." (PMID 35562873, 2022). "In this study, we want to investigate the pharmacological effect of PUN on psoriasis by using imiquimod (IMQ)-induced psoriatic mice model in vivo and tumor necrosis factor a (TNF-α) and interleukin-17A (IL-17A)-stimulated HaCaT cells in vitro." (PMID 35153790, 2022). "Biologics targeting IL-17A and TNF-α have demonstrated greater effectiveness than traditional strategies in treating psoriasis for decades." (PMID 35669784, 2022). "Both IL-17A and ROS were found to stimulate the activation of the NF-κB and PI3K/AKT/mTOR signaling pathways involved in the pathogenesis of psoriasis." (PMID 36498953, 2022).
psoriasis (continued). "The mRNA levels of psoriasis‐related inflammatory factors such as TNF‐α, IL‐23, IL‐17A, IL‐1β and IL‐6 were measured by RT‐PCR." (PMID 35023281, 2022). "Our data show that eCIRP expression was increased in the sera of psoriasis patients and imiquimod- (IMQ-) induced psoriatic mice and cells stimulated with proinflammatory cytokines (IL-1α, IL-17A, IL-22, oncostatin M, and TNF-α; mix M5)." (PMID 36110097, 2022). "It was found that there is a significant increase in IL-17A and HGF in HS comparatively similar to psoriasis." (PMID 36532043, 2022). "Normal human epidermal keratinocytes (NHEKs), HaCaT cells, and Ker-CT cells stimulated with M5 (IL-17A, IL-22, IL-1α, oncostatin M, and TNF-α) were used to establish a psoriasis model in vitro." (PMID 35586566, 2022). "This disrupts the IL17 pathway by blocking the activity of IL17A/E/F and shows high efficacy in the rapid improvement of psoriasis." (PMID 35563285, 2022). "We found that transcription levels of IL17A, IL17C, and IL17F were increased in psoriasis compared with normal skin, which was in parallel with their receptors IL17RA, IL17RC, IL17RD, and IL17RE." (PMID 36009523, 2022). "During this process, inflammatory cytokines: TNF‐α, IL‐1β, IL‐6, IL‐17a, and CXCL‐15 were infiltrated in skin and contributed to psoriasis." (PMID 35281792, 2022). "The symptoms and progression of psoriasis and colitis were significantly alleviated by ndSTAT1-TMD treatment, comparable to anti-IL-17A antibody treatment." (PMID 36591260, 2022). "As with TNFα, IL-17A is associated with barrier tissue chronic inflammatory diseases including psoriasis and IBD, and drugs inhibiting IL-17A signaling are currently used to treat patients." (PMID 36591258, 2022). "Another study compared the effects of secukinumab (IL-17A inhibitor), cyclosporine, or methotrexate (MTX) treatment on the left ventricular function and oxidative stress in patients with psoriasis." (PMID 35313642, 2022). "In summary, from a posttreatment point of view, these data identified IL-17A and TNF-α as critical molecules that maintain psoriasis plaques." (PMID 36483564, 2022). "Furthermore, we confirmed that IFNγ-sEVs reduced psoriasis symptoms including thickness, erythema, and scales of skin lesions; exhausted Th17 cells, increased Th2 cells; and reduced enrichment of inflammatory cytokines such as IL-17A, IFN-γ, IL-6, and TNF-α in both spleen and skin lesions in vivo." (PMID 35359454, 2022). "As cytokines represent important drivers of tissue inflammation in ncISD, we examined the expression of the major effector cytokines driving the common ncISD LP, AD, and psoriasis namely IFNG, IL13 and IL17A, respectively, in spatial resolution." (PMID 36513651, 2022). "A subset of epidermal CD8+ T cells expressing CCR6 (binding to CCL20 and mostly expressed by IL-17A-producing cells), CD103, and IL-23R was enriched in resolved psoriasis lesions." (PMID 36361639, 2022). "Expression of PI3 is increased in lesional skin and blood from patients with psoriasis and circulating levels of PI3 was shown to correlate with psoriasis disease severity, and is induced by IL-17A in keratinocytes." (PMID 35008981, 2022). "Treatment with RGRN-305 resulted in a marked inhibition of the IL-23, TNF-α, and IL-17A signaling pathways and the normalization of both histological changes and the gene expression profiles of psoriasis, further supporting that Hsp90 may serve as a novel target in the treatment of psoriasis." (PMID 36009046, 2022). "Imiquimod-induced psoriasis mice model and TNF-α or IL-17A induced HaCAT cells, an experimental model in vitro for psoriasis, were constructed." (PMID 34674702, 2021). "In this study, we investigated the effects of PSORI-CM02 on angiogenesis in IL-17A-stimulated human umbilical vein endothelial cells (HUVECs) and a mouse model of IMQ-induced psoriasis." (PMID 33995368, 2021).
psoriasis (continued). "IL17-A is known as a key effector in psoriasis, and the phosphorylation of STAT3 contained with its expression was increased in psoriasis lesions." (PMID 34445513, 2021). "We further explored the expression of PI3K isoforms in response to IL-22, IL-17A, TNF-α, and IFN-γ, pro-inflammatory cytokines deeply involved in psoriasis pathogenesis." (PMID 34685616, 2021). "MabE treatment inhibited the ear swelling of IMQ-treated mice, in addition to the mRNA expression of IL-17A, IL-1β and COX-2, which are known to be involved in the development and/or exacerbation of IMQ-induced psoriasis." (PMID 33836731, 2021). "In our study, there is downregulated expression of loricrin, filaggrin and involucrin, but elevated expression of keratin 5, keratin 14 and keratin 15 in IL-17A/IL-22/IFN-γ/TNF-α–induced HaCaT cells and in mice with IMQ-induced psoriasis." (PMID 34456715, 2021). "Furthermore, combined administration of anti-IL-17A monoclonal antibody (secukinumab and ixekizumab) reduced fasting glucose levels in imiquimod treated mice and improved hyperglycemia in patients with psoriasis, suggesting that IL-17 may be a key cytokine linking psoriasis and hyperglycemia." (PMID 34367173, 2021). "With respect to the inflammatory cytokines involucrate in the development of psoriasis, EGCG treatment reduced the level of IL-23, IL-22, IL-17F, and IL-17A." (PMID 34943117, 2021). "Th17 lymphocytes differentiate under the influence of IL-23, IL-1β, TGF-β and IL-6, secrete IL-17A, IL-17F, TNF-α, IL-21, IL-22, and IL-26, and they play a crucial role in the maintenance of psoriasis chronic inflammation." (PMID 34769005, 2021). "Given that TNF-α synergizes with IL-23 to promote IL-17A production by ILCs, it is likely that TNF-α and IL-23 inhibition are effective for psoriasis at least in part due to their ILC3 suppressive effects, thereby reducing IL-17A." (PMID 33749662, 2021). "Several cytokines are used for the generation of psoriasis-like HPK, i.e., IL-17A, TNF-α, IL-36γ, oncostatin, IFN-γ, IL-22 and IL-1α." (PMID 33801280, 2021). "Thus, the discovery that RORγt regulates the development of multiple lymphocyte lineages including IL-17A-producing immune cell populations provides compelling evidence that disruption of the RORγt/IL-17A/IL-23 axis may represent a viable therapeutic option for the treatment of psoriasis." (PMID 34752458, 2021). "It has been reported that PD-L1-Fc inhibits anti-CD3-induced IL-17A production in CD27–Vγ1– γδ T cells and shows great potential for the treatment of psoriasis in animal experiments." (PMID 34354596, 2021). "Positive correlations between MMP-3 level and proinflammatory cytokines IL-12p/70, IL-17A, and TNF-α recognized in our study confirm MMPs and Th1 and Th17 cytokines' cross talk in the inflammatory regulation in psoriasis." (PMID 34305455, 2021). "The pathogenesis of psoriasis is extremely complex and involves numerous immune and inflammatory mediators, including IL-1α, TNF-α, IL-17A, and IL-22." (PMID 34314383, 2021). "Th17-related products (IL-17A, MMP-12, PI3/elafin, and CCL20) are consistently upregulated in both acute and chronic intrinsic AD, but they are at lower levels than in psoriasis." (PMID 34072076, 2021). "Comparing DNA methylation profiles of “all psoriasis” patients before and after treatment with anti-TNF or anti-IL17A directed agents, we identified 1,907 DMPs (1,359 hypo- and 548 hypermethylated) annotated to 1,380 genes." (PMID 34746142, 2021). "This study was performed to observe the effects of FZHFZY on epidermal differentiation in IL-17A/IL-22/IFN-γ/TNF-α stimulated HaCaT cells and a mouse model of IMQ-induced psoriasis." (PMID 34456715, 2021). "In further studies, the same authors showed that IL-17A strongly upregulates the expression of IL-33 in the NHEK cells, suggesting involvement of IL-33 in the pathophysiology of psoriasis." (PMID 34884710, 2021).